HOTAIR (HOX transcript antisense RNA)
Diseases named in the same sentence as HOTAIR in open-access papers (continued):
Sharing a sentence is not in itself a finding about the gene and the disease.
melanoma (29 papers, 2013 to 2025). A malignant, usually aggressive tumor composed of atypical, neoplastic melanocytes. "HOTAIR downregulation has been associated with inhibiting cellular proliferation and inducing apoptosis in melanoma cells through the regulation of NF‐ĸB." (PMID 38193829, 2024). "The decreased expression of HOTAIR was found to be linked to melanoma cell growth inhibition and apoptosis induction via NF-/B control." (PMID 39777348, 2024). "Patients with advanced melanoma have plasma lncRNA HOTAIR, and there is a significant association between the state of the tumor and HOTAIR expression in melanoma tumors." (PMID 39777348, 2024). "In vitro, HOTAIR silencing has been shown to be associated with reduced potential for melanoma cell migration and invasiveness." (PMID 38601651, 2024). "These promising reports support the fact that HOTAIR has strong implications in the carcinogenesis of melanoma, making it a potential prognostic and diagnostic marker for MM." (PMID 33203119, 2020). "Knockdown of HOTAIR inhibits the motility and invasiveness of melanoma cells, and the latter is associated with decreased degradation of extracellular matrix." (PMID 23862139, 2013). "Together, our study shows that HOTAIR is overexpressed in metastatic tissue, which is associated with the ability of HOTAIR to promote melanoma cell motility and invasion." (PMID 23862139, 2013). "Furthermore, it was found that MALAT1 knockdown was followed by a decrease in melanoma cell migration, whereas HOTAIR knockdown was associated with suppression of cell motility and invasive potential, confirming the clinical utility of the studied lncRNAs." (PMID 35626352, 2022). "Fifty nontargeting sgRNAs were incorporated as negative controls as well as positive controls against five known melanoma-associated lncRNAs (BANCR, CDKN2B-AS1, HOTAIR, MALAT1, and SAMMSON)." (PMID 40552742, 2025). "HOTAIR leads to melanoma cell growth and metastasis by sponging miR‐152‐3p and activating the PI3k/Akt/mTOR signalling pathway." (PMID 38193829, 2024). "One such lncRNA is HOTAIR, which is highly expressed in lymph node metastatic melanoma tissues compared to primary melanoma tissues, with expression levels correlating with poor overall survival." (PMID 37629553, 2023). "At the same time, expression levels of miR-152-3p were upregulated through the knockdown of HOTAIR and tumor metastasis of melanoma was inhibited, suggesting lncRNA HOTAIR can enhance metastasis through interference with specific miRNA." (PMID 37629553, 2023). "For example, several lncRNAs have been dysregulated in melanoma, including HOTAIR, BANCR, UCA1, and MALAT-1, and related to invasion and metastasis." (PMID 35626352, 2022). "In melanoma, HOTAIR also functions as ceRNA for miR-157-3p and activates the c-MET oncogene and the PI3K/AKT/mTOR-signaling pathway, promoting invasion and metastasis." (PMID 35159386, 2022). "lncRNA HOTAIR was found in the plasma of patients with advanced melanoma, while HOTAIR expression in melanoma tumors strongly correlates with tumor stage." (PMID 35159386, 2022). "Cantile and colleagues verified the expression of the lncRNA HOTAIR in melanoma lesions compared to healthy tissue as well as its circulating levels in the blood of patients." (PMID 33503876, 2021). "Knockdown of HOTAIR suppresses motility of metastatic melanoma cell lines, which is manifested by decreased gelatinase activity of MMP2 and MMP9." (PMID 34638331, 2021). "HOTAIR has been related to the development of several solid cancers, such as breast cancer and melanoma, where it modulates cancer initiation, progression and drug resistance." (PMID 34638331, 2021). "In this regard, aberrant expression of HOTAIR was detected in lymphocytes surrounding metastatic tumour cells in melanoma patients." (PMID 33203119, 2020).
melanoma (continued). "It was confirmed via CCK-8 assay and DAPI staining assay that the number of cells in si-HOTAIR group was obviously reduced, which indicates that down-regulation of HOTAIR can reduce the proliferation of malignant melanoma cells." (PMID 33346222, 2020). "The effects of down-regulation of HOTAIR on the expressions of apoptosis-related genes and proteins in malignant melanoma cells were detected using qRT-PCR and Western blotting." (PMID 33346222, 2020). "The evidently higher early apoptosis rate was observed after down-regulation of HOTAIR, confirming that down-regulation of lncRNA HOTAIR can suppress the proliferation and promote the apoptosis of malignant melanoma cells." (PMID 33346222, 2020). "In fact, HOTAIR knockdown experiments led to a decreased melanoma cell motility and invasiveness in conjunction with a reduced capability to degrade the extracellular matrix." (PMID 28350340, 2017). "The main objective of this study was to verify the role played by HOTAIR in metastatic progression of melanoma and to evaluate the circulating levels of HOTAIR in the blood of patients with metastatic melanoma." (PMID 27461275, 2016). "They showed that knockdown of HOTAIR by siRNAs resulted in the reduction of motility and invasion of human melanoma cell line A375." (PMID 25859406, 2015). "The invasiveness of melanoma cells is also markedly suppressed by knocking down HOTAIR, as demonstrated by the Matrigel-based Boyden chamber assay." (PMID 23862139, 2013). "The role of HOTAIR in melanoma cell motility and invasion was further evaluated by knocking down HOTAIR with siRNAs." (PMID 23862139, 2013). "Among them, HOTAIR was significantly overexpressed in metastatic lymph nodes compared to matched primary melanoma (P < 0.01)." (PMID 23862139, 2013). "In conclusion, we demonstrate that HOTAIR lncRNA is predominantly upregulated in lymph node metastasis tissues compared with primary melanoma." (PMID 23862139, 2013). "Knockdown of HOTAIR resulted in the reduction of motility and invasion of human melanoma cell line A375, as assessed by wound healing assay and Matrigel-based invasion assay." (PMID 23862139, 2013). "Studies using wound healing assay demonstrate that knockdown of HOTAIR inhibits the migration of melanoma cells." (PMID 23862139, 2013). "Although further mechanistic investigation into the regulation of metastasis by HOTAIR is necessary, the observed prometastatic activity of HOTAIR in multiple preclinical model systems supports HOTAIR to be a potential target for melanoma metastasis therapy." (PMID 23862139, 2013). "Overall, these data suggest the potential role of HOTAIR as novel therapeutic agent in melanoma." (PMID 40282449, 2025). "HOTAIR overexpression contributes to the metastatic progression of melanoma." (PMID 40282449, 2025). "HOTAIR promotes the growth and metastasis of melanoma cells." (PMID 38601651, 2024). "HOTAIR expression is highly increased in metastatic melanomas and also in the lymphocytes surrounding the metastatic cells, suggesting a prominent role of the lncRNA in the invasion process by sponging miR-152-3p to upregulate the tyrosine kinase c-MET, known to be involved in metastasis." (PMID 35159386, 2022). "HOTAIR has been also identified in serum of melanoma patients, which indicates that its levels might potentially serve as a marker of melanoma incidence." (PMID 34638331, 2021). "However, the special function of HOTAIR in the progression of melanoma and its mechanism remain to be further studied." (PMID 33346222, 2020). "Higher HOTAIR expression was also detected in serum samples from patients with advanced melanoma, which suggests that this specific lncRNA may also serve as a prognostic and diagnostic marker for MM." (PMID 33203119, 2020).
melanoma (continued). "The early apoptosis rate in si-HOTAIR group (39.4%) was evidently higher than that in si-NC group (9.32%) and control group (4.73%) (P<0.05), confirming that down-regulation of lncRNA HOTAIR can suppress the proliferation and promote the apoptosis of malignant melanoma cells." (PMID 33346222, 2020). "In addition, the effects of down-regulation of HOTAIR on the expressions of apoptosis-related genes and proteins in malignant melanoma cells were detected using qRT-PCR and Western blotting, respectively." (PMID 33346222, 2020). "In this study, to explore whether down-regulation of lncRNA HOTAIR promotes the apoptosis of malignant melanoma cells, flow cytometry was performed in each group after transfection." (PMID 33346222, 2020). "The research results suggest that HOTAIR may become a potential therapeutic target for malignant melanoma." (PMID 33346222, 2020). "Down-regulation of lncRNA HOTAIR can inhibit the proliferation and promote apoptosis of malignant melanoma cells and suppress the NF-κB pathway, which may be related to the regulation on the NF-κB signaling pathway." (PMID 33346222, 2020). "Moreover, HOTAIR facilitates the growth and metastasis of melanoma cells via competitively binding to miR-152-3p and activating the downstream PI3K/Akt/mTOR signaling pathway." (PMID 33346222, 2020). "HOTAIR could exert a tumor promoting effect on malignant melanoma and act as a ceRNA suppressing miR-152-3p expression." (PMID 31649871, 2019). "Hence, in this study, we selected 6 well-documented lncRNAs associated with metastasis including MALAT1, HOTAIR, NEAT-1, HULC, MEG-3, and UCA1 to evaluate their expression in primary melanoma and matched lymph node metastasis tissues." (PMID 23862139, 2013). "Further, we investigated the role of HOTAIR in melanoma cell motility and invasion." (PMID 23862139, 2013). "Moreover, HOTAIR can target miRNAs to promote the metastasis of melanoma." (PMID 37629553, 2023). "Thus, HOTAIR can also promote melanoma cell invasion by regulating EMT." (PMID 37629553, 2023). "Moreover, high HOTAIR expression has been also found in intratumoral lymphocytes, and its expression has been correlated with the distance from the tumor site, suggesting that HOTAIR might influence melanoma immunogenicity." (PMID 34638331, 2021). "Moreover, miR-152-3p down-regulation could rescue the effects of HOTAIR silence on the process of malignant melanoma." (PMID 34419049, 2021). "Transfection with si-HOTAIR could reduce the expression of HOTAIR in malignant melanoma cells." (PMID 33346222, 2020). "Whether HOTAIR performs the same function in the progression of melanoma remains unknown." (PMID 23862139, 2013). "Broadly viewed, our literature analysis revealed that HOTAIR, H19, and MALAT1 are the main oncogenic lncRNAs studied, and correlated to the aggressiveness of melanoma phenotype and in the acquisition of drug resistance." (PMID 40282449, 2025). "The analysis of the literature showed that HOTAIR, MALAT1, and H19 are the oncogenic lncRNAs most studied in melanoma, while MEG3 is an important tumor suppressor decreased in this cancer." (PMID 40282449, 2025). "Several lncRNAs, such as HOTAIR, MALAT1, and BANCR have been reported to be dysregulated in melanoma." (PMID 38561355, 2024). "Other studies identified the role of HOTAIR, MALAT1, BANCR, ANRIL, SPRY‐IT1, SAMMSON, UCA1, and SLNCR1 in melanoma patients and cell lines." (PMID 39764216, 2024). "Although the role of HOTAIR in acquired drug resistance is currently unknown, it could represent a promising therapeutic target for MM, considering it was found particularly enriched in lymph-node metastases and its knockdown suppressed melanoma cell motility, significantly decreasing invasion." (PMID 33203119, 2020). "Several studies have identified known lncRNAs that are abnormally expressed in melanoma, such as SAMMSON, HOTAIR, SLNCR1, BANCR, SPRY4-IT1, ANRIL, Llme23, UCA1, MALATA1, GAS5, H19, CASC15, PTENP1, and MIR31HG." (PMID 28225791, 2017).
melanoma (continued). "Interestingly, three of these identified pathways were, i) cancer metastasis signaling, ii) HOTAIR regulatory pathway, and iii) regulation of EMT pathway, suggesting a potential role of PLK1 in EMT and melanoma metastasis." (PMID 38184733, 2024). "HOTAIR expression was found to be significantly higher in lymph node metastases compared to primary melanoma, whereas several other lncRNAs, including MALAT1, Urothelial carcinoma-associated 1 (UCA1), and nuclear-enriched transcript 1 (NEAT1), showed no change in their expression patterns." (PMID 28350340, 2017).
breast tumors (28 papers, 2012 to 2023). "HOTAIR is increased in expression in primary breast tumors and metastases, and loss of HOTAIR can inhibit cancer invasiveness." (PMID 26213588, 2015). "This system allowed us to manipulate HOTAIR overexpression using Dox in mice with breast tumors and study HOTAIR function in tumor progression and metastasis in a controlled manner." (PMID 36579891, 2022). "For example, HOTAIR has been shown to be a factor of both metastasis and survival in primary breast tumors." (PMID 36412909, 2022). "In this manner, we can manipulate HOTAIR expression in vitro in late stage breast tumor cells in the same genetic background as in our iHOT-PyMT mouse model." (PMID 36579891, 2022). "Analysis of The Cancer Genome Atlas (TCGA) database using cBioPortal confirmed that HOTAIR was upregulated in clinical breast tumors relative to normal mammary tissues." (PMID 32466537, 2020). "HOTAIR is highly expressed in primary as well as metastatic breast tumors, and high level of expression in primary breast tumors is a powerful predictor of subsequent metastasis and death." (PMID 32872482, 2020). "For instance, the expression of the lncRNA called HOTAIR was shown to be higher in primary breast tumors and metastases, and the HOTAIR expression level was proven to be a powerful predictor of eventual metastasis and death." (PMID 29986541, 2018). "This article proposed that the lncRNA HOTAIR was increased in expression in primary breast tumors and metastases, and the HOTAIR expression level is a powerful predictor of eventual metastasis and death." (PMID 29992161, 2018). "Expression analysis between breast invasive tumor and normal tissues showed that the HOTAIR is significantly overexpressed in breast tumors compared to normal tissues." (PMID 29209357, 2017). "There are just a few studies with limited number of samples indicating the differentiated expression of HOTAIR in breast tumors compared to normal tissues." (PMID 29209357, 2017). "qRT-PCR detections showed that Dp administration significantly decreased the level of HOTAIR in xenografted breast tumors in athymic mice." (PMID 27388461, 2016). "For example, HOTAIR expression is increased in primary breast tumors and metastases and its expression level in primary tumors is a powerful predictor of eventual metastasis and death." (PMID 25890171, 2015). "HOTAIR expression is increased in primary breast tumors and metastases (as much as 2000-fold), and HOTAIR expression in primary tumors is a powerful predictor of eventual metastasis and death, independent of known clinicopathologic risk factors." (PMID 25334066, 2014). "HOTAIR was found to be highly up-regulated in primary, as well as metastatic, breast tumors, and its elevation correlated with both metastasis and poor survival rate." (PMID 25334066, 2014). "We continued to treat the mice with Dox for 3–4 months, exposing mice to continual HOTAIR overexpression, to investigate whether HOTAIR can affect breast tumor progression." (PMID 36579891, 2022). "HOTAIR overexpression has been demonstrated in primary breast tumors and metastases." (PMID 28036281, 2017). "The lncRNA, HOTAIR, showed increased expression in primary breast tumors and metastases." (PMID 26908441, 2016). "Overexpression of HOTAIR has been observed in Tam resistant breast tumors when compared to primary ones, and its downregulation significantly suppressed growth in Tam resistant model cell lines, suggesting it may represent a therapeutic target for Tam-resistant tumors." (PMID 34359587, 2021). "First, we found that primary breast tumor weight and tumor numbers were not affected by continuous exposure to elevated levels of HOTAIR." (PMID 36579891, 2022). "HOTAIR is transcribed from the genomic HOXC locus and represses expression in the distal HOXD locus and genes located on other genomic loci, resulting in decreased expression of multiple genes to promote metastasis of breast tumors." (PMID 32466537, 2020).
breast tumors (continued). "It was found that the expression of HOTAIR is down-regulated in LuminalA, LuminalB, and normal like breast tumors subtypes (Data not shown)." (PMID 29209357, 2017).